MYH6 (myosin heavy chain 6)
Diseases named in the same sentence as MYH6 in open-access papers (continued):
Sharing a sentence is not in itself a finding about the gene and the disease.
heart failure (continued). "We found that the incidence of heart failure was higher when the expression levels of MYH6 were decreased, and this difference was statistically significant (p < 0.05)." (PMID 34697898, 2021). "The switch from Myh6 to Myh7 expression is an important feature of specific sets of GE related to heart failure per se." (PMID 33260869, 2020). "C.927-2A>G in MYBPC3 (MAF = 0.18%) associates with cardiomyopathy, heart failure, ventricular tachycardia and atrial fibrillation (AF), and p.Arg721Trp (MAF = 0.34%) in MYH6 with sick sinus syndrome (SSS), AF and coarctation of the aorta." (PMID 31641117, 2019). "Altered MYH6 expression is an important pathway in the molecular mechanism of heart failure and myocardial recovery." (PMID 31687497, 2019). "Quantitative PCR (qPCR) analysis of csPLA-Tg myocardium showed that there was reduced mRNA expression of Myh6 and increases in Myh7, Nppa, and Nppb mRNA, consistent with heart failure." (PMID 31622279, 2019). "As in the neonatal Gata4/6 loss-of-function experiment, Myh7 and Nppa were highly upregulated in GATA4/6 knockout hearts, while Myh6 was highly downregulated, consistent with changes observed in heart failure." (PMID 26023924, 2015). "In the context of heart failure, cardiomyocyte damage or apoptosis may lead to the release of intracellular MYH6 into the bloodstream, resulting in elevated plasma MYH6 levels." (PMID 40406620, 2025). "Transcript levels of several established biomarkers, including Spp1, Sfrp1, Sfrp2, Tnc, Vim, Mmp9, and Tnfrsf1a, and several inflammatory markers that are known to be activated in heart failure, such as Cd44, Cd83, Ccl7, Irf7, and Nr4a2, were upregulated in the Myh6-McmTamDspfl/fl cardiomyocytes." (PMID 40608429, 2025). "Echocardiography revealed a profound dilated cardiomyopathy and heart failure in Ptpmt1fl/fl/Myh6-Cre+ mice, including both systolic and diastolic LV dilation, thinning of ventricular walls, depression of EF and FS, arrhythmias, and impaired myocardial contraction." (PMID 37672386, 2023). "On the other hand, STAT3 activates the transcription regulator GATA4, thereby upregulating the expression of NPPA, MYH7, and MYH6, which interacted with each other to regulate the structure and function of the sarcomere, resulting in heart failure and arrhythmias." (PMID 36034815, 2022). "This means that MYH6 may be one of the important targeted gene of OMECAMTIV MECARBIL in the treatment of heart failure." (PMID 34970603, 2021). "Moreover, a switch involving decreased Myh6 and Serca2a and increased Myh7 and Pln transcripts was reported in conditions of hypertrophy and heart failure." (PMID 34395557, 2021). "NKX2-5 and MYH6 were involved in failure of heart and arrhythmia, respectively." (PMID 32423033, 2020). "Additionally, the inflammatory and immune responses accompanying heart failure may also influence the expression and release of MYH6." (PMID 40406620, 2025). "In another cohort of studies, AUTR Myh6-Cre derived mutants manifested both heart failure and variable survival phenotypes, rendering it challenging to determine whether the aspects of the survival phenotypes resulted from ectopic Cre expression or were secondary effects of heart failure." (PMID 39323506, 2024). "Hypertrophy of adult hearts is also associated with Myh6 downregulation and Myh7 induction, returning to a fetal state of MHC expression and thus controlling the expression of MHC may be an attractive approach for heart failure therapy." (PMID 35858921, 2022). "Therefore, we can speculate that the downregulation of MYH6 expression is closely related to the occurrence of heart failure." (PMID 34697898, 2021). "The importance of MYH6, despite the low level of MYH6 expression in human ventricles, is also highlighted in other studies that have observed an increase in MYH6 expression in heart failure patients who improved after cardiac resynchronization therapy or medical treatment." (PMID 26347658, 2015).
heart failure (continued). "In the GSE59867 data set, MYH6 expression was lower in CAD patients than in AMI patients and lower in heart failure (HF) patients than in non‐HF patients." (PMID 34697898, 2021). "In our study, inhibition of TBX5 was shown to dysregulate several genes such as DES, NKX2-5, ACTC1, MYH6, ATP2A2 and HSPB7, which further contributed to ICM-related diseases such as failure of heart and degeneration of heart." (PMID 32423033, 2020). "In support of the reduced cardiac output, female KI mice presented an increase in the expression of heart failure‐related genes Nppa, Nppb, and Myh6, while this was not seen in male mice." (PMID 40674274, 2025). "Intriguingly, we observed a drastic decrease in the Myh6/Myh7 ratio but no change in the expression of Nppa, Col1a1, and Postn in cKO hearts at the early stage, consistent with no cardiac fibrosis or heart failure at this time." (PMID 38201239, 2023). "It has been described that MYH6 protein is detectable only in patients without heart failure and undetectable in failing hearts, supporting the result of cardiac dysfunction in our study." (PMID 34537857, 2021). "MYH6 and ADRB1 down-regulation are key components of contractile dysfunction in heart failure." (PMID 31687497, 2019). "In contrast, pathological remodelling is characterised by a pronounced transcriptional shift: MYH6 mRNA is significantly downregulated to just a few percent of total myosin transcripts, while MYH7 mRNA increases to nearly 100%, particularly in end-stage heart failure." (PMID 41295372, 2025). "Moreover, this histological observation was supported by increased expression levels of heart failure markers, such as ANP and BNP, and physio-functional markers, such as Atp2a2, Myh6, and Myh7, which indicate contractility, cardiomyocyte size and LV wall thickness, respectively." (PMID 35008972, 2022). "However, during the 180‐day follow‐up period, we found that MYH6 expression was lower in patients with heart failure than in those without heart failure (p < 0.01)." (PMID 34697898, 2021). "Because control Tg mice such as Myh6-CreERT2 mice or CALELD mice fed by tamoxifen-chow did not develop hypertrophy (data not shown) and that tamoxifen treatment was for only two weeks, tamoxifen by itself unlikely caused the heart failure." (PMID 27494843, 2016). "Likewise, the expression of both the B-type natriuretic peptide gene (Bnp) and of Myh6/Myh7 was induced equally in both groups after TAC, clearly demonstrating that these TBC1D10C TG mice are not protected from TAC-induced hypertrophy or heart failure." (PMID 27667030, 2016).
cardiomyopathy (57 papers, 2011 to 2025). A disease of the heart muscle or myocardium proper. "PBM appears to oppose these changes, as indicated by its modulation of the sarcomeric MYH6 gene expression, which is linked to the development of cardiomyopathy." (PMID 40722850, 2025). "We observed significant downregulation of MYH6, a gene encoding α-myosin heavy chain and a key determinant of cardiac contractility, across multiple cardiomyopathy subtypes." (PMID 41283336, 2025). "Pathogenic variants in the cardiomyopathy-associated genes, particularly MYH6, are associated with both the development of congenital heart defects and impaired myocardial function in these patients." (PMID 41153298, 2025). "eliminate the mutant allele and delay the progression of cardiomyopathy in Myh6-targeted knock-in mice." (PMID 34760939, 2021). "Mutations in MYH6 have been reported in patients with both dilated and hypertrophic phenotypes of cardiomyopathy." (PMID 31948008, 2020). "It has been shown that mutations in MYH6 gene cause cardiomyopathy both in humans and Xenopus suggesting a well-conserved disease mechanism." (PMID 31620018, 2019). "In this report we showed the effects of a human cardiomyopathy gene (MYH6) and a known teratogen, EtOH (known to cause Fetal Alcohol Syndrome) on early cardiac development using HCSA imaging." (PMID 31620018, 2019). "In contrast, mutational analyses of MYH6 in probands with cardiomyopathy found that the majority of mutations were located in the myosin rod or neck whereas only very few were detected in the head." (PMID 22194935, 2011). "Some studies link the increase in Myh6 expression with cardiomyopathy, and gene mutations may cause coronary heart disease." (PMID 38892086, 2024). "Next, rare variant burden testing of 56 known cardiomyopathy genes demonstrated enrichment in MYH6 in 23 HLHS probands, 12 of whom had either a MYH6 variant co-segregating with familial CHD, compound heterozygosity, or synergistic heterozygosity with FLNC, which is also a cardiomyopathy gene." (PMID 35448093, 2022). "Mutations of myh6 and myh7 in zebrafish are known to be associated with cardiomyopathy." (PMID 34775978, 2021). "Potentially pathogenic variants in a handful of genes associated with cardiomyopathy, especially MYH6, have been associated with both the development of congenital heart defects and the disease course in the form of impaired myocardial dysfunction in these patients." (PMID 33194928, 2020). "Defect in myosin heavy chain 6 causes atrial septal defect 3 and cardiomyopathy." (PMID 31272500, 2019). "In addition, the cardiomyopathy related MYH6-A1004S and the MYBPC3-A833T mutations were also found in one and two unrelated subjects with ASDII, respectively." (PMID 22194935, 2011). "Importantly, in addition to cilia-associated genes, we identified recessive variants in four genes previously implicated in cardiomyopathy (MYH6, UNC45B, MYO18B, and MYBPC3) that are expressed in embryonic cardiomyocytes; RGs in these genes contributed to left-sided CHD phenotypes." (PMID 40030011, 2025). "Research has found that Myosin Heavy Chain 6 expression levels are elevated in the hearts of rats with an isoproterenol-induced cardiomyopathy model, and that Astragaloside IV combined with DS downregulates Myosin Heavy Chain 6 expression in the myocardium." (PMID 40687556, 2025). "Seven variants (41%) were detected in genes associated with cardiomyopathies including CSRP3, LAMA4, MYH6, MYBPC3, TNNI3, TNNI3K, and TNNT2." (PMID 39272661, 2024). "The downregulation of two of the key cardiomyopathy stress genes, Myh6 and Atp2b4 (PMCA), in Het mice treated with HFD was confirmed at the protein level (Fig. EV3A–D)." (PMID 38724625, 2024). "Eight (11.59%) hits concerned substrate defects, such as fibro-adipose substitution or RV end-diastolic volume (EDV), and they mainly involved genes associated with cardiomyopathies and muscle dysfunction, including TRIM63, MYH6, SGCD and LAMA2." (PMID 36008935, 2022).
cardiomyopathy (continued). "Molecular marker analyses demonstrated a significant decrease in the expression of the hypertrophic and cardiomyopathy marker genes Nppa, Nppb, and Myh7/Myh6 in AAV-LncHrt-treated hearts." (PMID 34379189, 2021). "Marker analyses demonstrated a significant increase in the expression of cardiomyopathy marker genes such as Nppa, Nppb, and Mhy7/Myh6 after LncHrt knockdown, which supports our observation that knock-down of LncHrt adversely affects cardiac function." (PMID 34379189, 2021). "A transgenic mouse model that expresses a TCR specific for myosin heavy chain 6 (MYH6) was reported to develop spontaneous cardiomyopathy." (PMID 33614621, 2020). "It has been reported that the mutations in the MYH6 gene associated with sinus venosus atrial septal defect (ASD type III), hypertrophic (HCM) and dilated (DCM) cardiomyopathies." (PMID 29969989, 2018). "This mutation is located at the extremely conserved region in MYH6 gene in Primates, Myosin heavy chain-α isoform (MHC-α), and it is presumed to result in a truncated protein that is associated with Cardiomyopathy and ASD type 3 (OMIM: 614089, 613,251)." (PMID 29969989, 2018). "In conclusion, the Crif1 conditional knockout mice generated by using the two different cre transgenic lines, Ckmm-cre and Myh6-cre/Esr1, develop cardiomyopathy due to impaired mitochondrial respiration." (PMID 23308255, 2013). "We set out to determine whether the DDR pathways were activated and pathogenic in an established mouse model of desmoplakin (DSP) cardiomyopathy generated upon deletion of the Dsp gene in cardiomyocytes (Myh6-MerCreMerTam Dspfl/fl; Myh6-McmTamDspfl/fl)." (PMID 40608429, 2025). "Despite its low expression in non-failing ventricles, MYH6 pathogenetic variants have been implicated in a spectrum of cardiomyopathies, suggesting a role in ventricular function under pathological conditions." (PMID 40004541, 2025). "Furthermore, the expression of the MYH6 gene changes with the improvement of clinical symptoms during the treatment of cardiomyopathy or HF." (PMID 41158506, 2025). "The phenotype in the Myh6-McmTam:DspF/F mouse model resembles the phenotype of DSP-related cardiomyopathy, which is characterized by the prominence of cell death, inflammation, myocardial fibrosis, left-dominant or biventricular cardiomyopathy, and progressive heart failure." (PMID 36818425, 2023). "In the family of our study, the parents carrying with only SYNE1 p.S4607F or LDB3 p.M456R/MYH6 p.S180Y mutations presented with no phenotype of cardiomyopathy or arrhythmia." (PMID 33949037, 2021). "As variants in the cardiomyopathy associated contractility gene MYH6 have been associated with poor prognosis in HLHS and other CHD patients, we hypothesized that a cardiomyopathy gene panel could function as a prognostic tool in HLHS." (PMID 33194928, 2020). "Moreover, when we analyzed the ratio of Myh7 / Myh6 expression, a common ratio investigated in cardiomyopathy readouts, we observed between 15 and 20 fold differences in diabetes, which was significant in WT mice and trending in KO animals (WT: p < 0.05, KO: p = 0.1)." (PMID 38054572, 2023). "Although numerous studies have consistently reported this isoform switch in various cardiomyopathies—including DCM, hypertrophic cardiomyopathy (HCM), ischaemic cardiomyopathy (ICM), and aortic stenosis—comparative data on MYH6/MYH7 expression ratios in healthy human LVs remain limited." (PMID 41295372, 2025). "MYH6 was downregulated across all three cardiomyopathy groups, while NPPA was upregulated in DCM and HCM but not significantly in PPCM." (PMID 41283336, 2025). "To investigate the role of Slc25a49 in Dox‐induced cardiomyopathy, we generated mice with tamoxifen‐induced, cardiac‐specific Slc25a49 gene knockout by interbreeding Slc25a49flox/flox mice with Myh6‐Cre/ERT2 transgenic mice (Slc25a49flox/flox; Myh6‐Cre/ERT2)." (PMID 40184586, 2025).
cardiomyopathy (continued). "Furthermore, they compared the genes with consistent change across all three cardiomyopathies to the druggable genome, resulting in 39 druggable genes (10 up-regulated and 29 down-regulated) including CYD2J2, MYH6, COL14A1, and SPARCL1." (PMID 37421484, 2024).
hypertrophic cardiomyopathy (37 papers, 2008 to 2025). "MYH6 encodes the embryonic cardiac α-myosin heavy chain, and has previously been associated with a small number of patients with dilated and hypertrophic cardiomyopathy, ASD, and HLHS." (PMID 40127276, 2025). "MYH6, encoding α‐myosin heavy chain, has also been reported in patients with hypertrophic cardiomyopathy, but its causal role in hypertrophic cardiomyopathy is less certain." (PMID 39981966, 2025). "Studies have also reported additional mutations in Myh6 linked to both hypertrophic cardiomyopathy and dilated cardiomyopathy." (PMID 38110334, 2023). "In a mouse model of hypertrophic cardiomyopathy caused by an Myh6 mutation, a reduction of 28.5% of mutant Myh6 was enough to prevent the development of HCM." (PMID 35409410, 2022). "Previously, it has been reported that the mutations in MYH6 are associated with late-onset hypertrophic cardiomyopathy, atrial septal defects and sick sinus syndrome." (PMID 29969989, 2018). "MYH6 (OMIM: 160710) mutations in humans are known to cause familial hypertrophic cardiomyopathy and atrial septal defects." (PMID 26815362, 2016). "For example, correcting pathogenic mutations like those in the MYH6 gene associated with hypertrophic cardiomyopathy necessitates efficient delivery of gene editing agents specifically to cardiac muscle cells, enabling restoration of normal myocardial function." (PMID 40465697, 2025). "Studies have shown that expression of MYH6 was associated with hypertrophic cardiomyopathy." (PMID 34218797, 2021). "Myh6 mutations lead to dilated and hypertrophic cardiomyopathy, as well as atrial septal defect." (PMID 34542814, 2021). "MYH6 and MYH7, which encode cardiac myosin heavy chains and are frequently mutated in hypertrophic cardiomyopathy (HCM), were edited in 10% of studies to correct sarcomeric dysfunction." (PMID 40465697, 2025). "CACNA1D, MYH6 and SCN10A had a cardiovascular disease as their top disease association (sinoatrial node dysfunction, hypertrophic cardiomyopathy and AF, respectively)." (PMID 38969939, 2024). "The KEGG pathway enrichment analyses results showed that MYH6 was significantly enriched pathway of cardiac muscle contraction, hypertrophic cardiomyopathy and dilated cardiomyopathy." (PMID 32631246, 2020). "Genes involved in hypertrophic cardiomyopathy such as Myh6 and Acta2, cardiac fibrosis such as Mmp2 and Col3a1, were all highly up-regulated by AB surgery, and hispidulin treatment significantly down-regulated these genes." (PMID 33324687, 2020). "The investigators then intraperitoneally injected sgRNA targeting Myh6 loaded in an adeno-associated virus (AAV) vector, subsequently inducing cardiac-specific gene modification at the Myh6 locus, finally leading to hypertrophic cardiomyopathy." (PMID 32296011, 2020). "Myh6 encodes MHC-α, particularly in human cardiac atria, the major thick filament protein, whose mutations are associated with late-onset hypertrophic cardiomyopathy, atrial septal defects, and sinus node disorder." (PMID 30400228, 2018). "In a knock‐in mouse model of hypertrophic cardiomyopathy resulting from a dominant single nucleotide substitution in the Myh6 gene, the disease was prevented by silencing only 30% of the mutant transcript." (PMID 29246969, 2018). "In mice, inactivation of the specific mutant MYH6 transcript suppresses hypertrophic cardiomyopathy." (PMID 26607727, 2015). "With respect to hypertrophic cardiomyopathy, Serca2 and Myh6 are major determinants of both cardiac relaxation and contraction." (PMID 23335977, 2013). "Mutations in MYH6 and MYH7 are associated with hypertrophic cardiomyopathy." (PMID 37701139, 2023). "However, immunostaining showed few deposition of globotriaosylceramide in left ventricular myocardium, and gene mutations in the disease genes for hypertrophic cardiomyopathy (HCM), MYBPC3 and MYH6, were detected." (PMID 27160240, 2016).